MMP9 (matrix metallopeptidase 9)
Diseases named in the same sentence as MMP9 in open-access papers (continued):
Sharing a sentence is not in itself a finding about the gene and the disease.
bladder cancer (continued). "Previous studies have shown that low levels of miR-124 upregulated MMP-2 and MMP-9 in bladder cancer cells and favored their invasion." (PMID 35620289, 2022). "The results of Immunohistochemical staining illustrated higher expression of MMP9 in bladder cancer tissues compared to that in normal bladder epithelial tissues, and the same was validated by Western blot." (PMID 35504875, 2022). "Through gain- and loss-of-function approaches, we found that LINC00478 up-regulation diminished the malignant phenotype of bladder cancer cells in vitro, and further inhibited xenograft tumor growth and metastasis in vivo by repressing MMP9." (PMID 35504875, 2022). "Lastly, an in vivo tumor metastasis test was carried out to study the effect of LINC00478 and MMP9 on the metastatic capacity of bladder cancer cells." (PMID 35504875, 2022). "Overall, these findings indicated that LINC00478 up-regulation represses the bladder cancer cell malignant phenotype by inhibiting MMP9." (PMID 35504875, 2022). "In an effort to explore the effect of LINC00478 on the MMP9 expression in bladder cancer, we over-expressed LINC00478 alone or with MMP9 in T24 cells." (PMID 35504875, 2022). "Using univariate survival analysis, we found a significant correlation between prognosis and MMP-9 expression in many cancer types, including uterine, kidney, skin, brain, liver, and bladder cancers." (PMID 35178444, 2022). "We further analyzed the expression of LINC00478 and matrix metalloprotein 9 (MMP9) in bladder cancer tissues and cell lines and observed a significant decline in LINC00478 expression and an elevation in MMP9 expression." (PMID 35504875, 2022). "MMP9 overexpression is required for the advancement of a variety of tumor kinds, consisting of esophageal squamous cell carcinoma, bladder cancer, and intrahepatic cholangiocarcinoma." (PMID 36059672, 2022). "Signal transducer and activator of transcription 3 (STAT3) signaling pathway was reported to induce chemoresistance and EMT via MMP-9 induction in bladder cancer." (PMID 35586209, 2022). "Further investigation of the EMT markers E-cadherin and MMP9 indicated decreased IQGAP2-induced EMT in bladder cancer cells." (PMID 36362301, 2022). "Uc.8 is a natural decoy for miR-596; thus uc.8 upregulation results in increased expression of MMP9, increasing the invasive potential of bladder cancer cells." (PMID 35626721, 2022). "Mast cells in tumor microenvironment were reported to strengthen bladder cancer metastasis by regulating ERβ/CCL2/CCR2 EMT/MMP9 signals." (PMID 34112144, 2021). "Salidroside significantly increased the autophagy of T24 cells through the autophagy/PI3K/Akt and MMP-9 signaling induced bladder cancer cells apoptosis." (PMID 35252345, 2021). "Given the inhibitory effect of MSSV on the migratory and invasive abilities of bladder cancer cells, we examined MMP-9 expression in the presence of MSSV." (PMID 33430488, 2021). "In comparison with the untreated cells, MSSV-treated bladder cancer cells had a lower level of MMP-9 secretion." (PMID 33430488, 2021). "In the present study, we found that BA suppressed migration and invasion in all three bladder cancer cells, as well as down-regulated the expression of the metastatic-related proteins including Snail, Slug, and MMP-9." (PMID 33806566, 2021). "For example, NETs can promote bladder cancer resist to radiotherapy; MMP-9 is significantly expressed in high-grade bladder cancer compare with that in low-grade ones." (PMID 34869390, 2021). "Univariate analysis indicated age, race, MMP9, IL8, VEGFA, CA9, PAI1, ApoE, A1AT, ANG and MMP10 were associated with bladder cancer." (PMID 33823873, 2021). "MMP-9 has been considered as a well-known proteolytic enzyme that plays a critical role in inducing migration and invasion of bladder cancer cells." (PMID 33430488, 2021).
bladder cancer (continued). "Morin decreases CDK2, CDK4, cyclin D1, and cyclin E via modulation of the p21/WAF1 pathway, suppressing c-Jun N-terminal kinase (JNK) and AKT phosphorylation, and preventing MMP-9 expression by repressing NF-κB, SP-1, and AP-1 in EJ bladder cancer cells." (PMID 33996570, 2021). "Regulatory components that exist in the MMP‐9 gene contain the binding site for NF‐κB, which has been proved to drive MMP‐9 production in macrophages, neutrophils, cardiomyocytes, fibroblasts, and bladder cancer cells." (PMID 33900049, 2021). "MMP-9 secretion in the conditioned medium was investigated by gelatin zymography in MSSV-treated bladder cancer cells." (PMID 33430488, 2021). "To further investigate the regulatory mechanism of MMP-9 in MSSV-treated bladder cancer cells, we employed EMSA assay." (PMID 33430488, 2021). "Recently, one study revealed that TAM infiltration in the TME elevates CXCL8, promoting bladder cancer cell migration and invasion via the secretion of MMP9, VEGF, and E-cadherin." (PMID 32943996, 2020). "Studies in human beings document an association between increased urinary activities of MMP‐2 and MMP‐9 and early‐stage bladder carcinoma." (PMID 32468592, 2020). "Mechanistically, circ0001361 directly interacts with miR-491-5p to upregulate MMP9 expression, promoting bladder cancer cell invasion and metastasis both in vitro and in vivo." (PMID 32943996, 2020). "Mechanistically, circ-HIPK3 enrichment can abundantly sponge miR-558 to decrease heparanase (HPSE), VEGF, and matrix metallopeptidase 9 (MMP9) levels, thus effectively suppressing the invasive abilities and angiogenesis of bladder cancer cells." (PMID 31937318, 2020). "T24-Exos or J82-Exos also induced the expression of the EMT-transcription factors Slug, Snail, Twist and Zeb2, which ultimately suppressed E-cadherin expression but promoted N-cadherin, vimentin, MMP2 and MMP9 expression in bladder cancer cells." (PMID 32517366, 2020). "This was also demonstrated by ELISA at the protein level, indicating that CXCL8 can promote bladder cancer invasion by stimulating bladder cancer cells to secrete MMP-9." (PMID 32201645, 2020). "In the present study, SPHF significantly inhibited MMP-9 gelatinase activity in EJ bladder cancer cells." (PMID 32708058, 2020). "We next investigated MMP-9 regulation in SPHF-treated EJ cells using the EMSA assay due to the known role of MMP-9 expression in bladder cancer migration and invasion." (PMID 32708058, 2020). "In the present study, nimbolide treatment of bladder cancer cells significantly reduced the expression of MMP-9." (PMID 31391858, 2019). "Melatonin can inhibit the tumorigenesis of bladder cancer and renal cell carcinoma metastasis by downregulating MMP-9 expression through different signaling pathways." (PMID 31811815, 2019). "Because MMP-9 activity is a key regulator in the progression of bladder cancer, we investigated its regulatory mechanism in both nimbolide-treated bladder cancer cell lines." (PMID 31391858, 2019). "We also found regorafenib significantly reduces tumor growth, NF‐κB activation, and protein levels of tumor progression‐associated proteins (MMP‐9, XIAP, VEGF, and Cyclin‐D1) in bladder cancer in vitro and in vivo." (PMID 30801954, 2019). "It is considered that MMP-9 is a crucial factor in the progression and development of bladder cancer." (PMID 31391858, 2019). "In bladder cancer, uc.8+ has been shown to be involved in bladder cancer progression through the stabilization of MMP9 by targeting miR-596." (PMID 31167408, 2019). "During migration and invasion of bladder cancer cells, MMP-9 regulation is controlled via activation of the transcription factors NF-κB, Sp-1, and AP-1." (PMID 31391858, 2019). "Fucoidan-treated bladder cancer cell lines showed a decrease in MMP-9 expression but, at the same time, an increase in phosphorylated AKT protein level in vitro." (PMID 30621045, 2019).
bladder cancer (continued). "TNF-α-induced MMP9 expression is dependent on P38 signaling in human urinary bladder cancer 5637 cells or human monocytes." (PMID 31307477, 2019). "We found that MMP-9 dimer and MMP-9 were independent predictors for distinguishing between patients with prostate and bladder cancer (P < 0.001 for each)." (PMID 30197761, 2018). "MMP-9 and N-cadherin, which play crucial roles in cancer cell migration and invasion in bladder cancer, are reportedly modulated by GTPs in bladder cancer cell lines." (PMID 30103466, 2018). "MMP-2 and MMP-9 were reported to play important roles in bladder cancer cell invasion and metastasis." (PMID 28178653, 2017). "So globally, mast cells promote metastasis of bladder cancer in mice in a CCL2/CCR2/EMT/MMP9‐dependent mechanism." (PMID 28599100, 2017). "In this study, we investigated the potential suppressive effects of GE in relation to cell cycle, signaling pathways, and transcription factor-mediated MMP-9 regulation in bladder cancer EJ cells." (PMID 28187175, 2017). "We selected MMP9 SNPs for genotyping in our study after reviewing the literature of more common cancers, such as bladder cancer, where a large meta-analysis was written considering many genetically diverse populations." (PMID 29138529, 2017). "Matrix metalloproteinases including MMP-9 were previously reported as key regulators in aggressiveness and poor prognosis of bladder cancers." (PMID 28680385, 2017). "Cancer development and progression are associated with the involvement of both epithelial-mesenchymal transition (EMT) and tumor microenvironment of which NGAL/MMP-9 complex represents the main player in bladder cancer." (PMID 27602581, 2016). "We recently observed that NGAL/MMP-9 complex plays an active role in proliferation, differentiation, tissue development, and tumor development of bladder cancer progression." (PMID 27602581, 2016). "For instance, we have recently demonstrated the involvement of NGAL and MMP-9 in bladder cancer development and progression." (PMID 27602581, 2016). "The use of mirDIP software has also allowed us to identify differentially expressed miRNAs that were down-regulated in bladder cancer and therefore responsible for the increase of gene expression of MMP-9 and NGAL in cancer patients." (PMID 27602581, 2016). "Loss of expression of miRNA-141 and miRNA-200b was associated with increased invasion and migration ability, upregulated MMP-2, MMP-9, vimentin and N-cadherin expression, and downregulated E-cadherin expression in bladder cancer cell lines." (PMID 25884322, 2015). "Ras induced RbAp46 expression increases invasion of the bladder cancer T24 cells and MMP-9 activity was increased, which was confirmed by specific lentiviral shRNAs inhibitors against Ras and RbAp46." (PMID 25885317, 2015). "Relative to control cases, a reduction in SDC1 and overexpression of MMP9, MMP10, SERPINE1, IL8, APOE, SERPINA1, ANG were associated with high stage bladder cancer." (PMID 25387487, 2014). "Urinary levels of both MMP-3 and MMP-9 were significantly elevated in all bladder cancer patients compared with controls." (PMID 25135219, 2014). "There was a significant increase of the mean value of urinary MMP9 level for the whole 70 bladder cancer cases (7.99 ng/ml) when compared to that of the control group (0." (PMID 25135219, 2014). "We suspected that the expression of NDRG2 significantly suppresses the MMP-2 and MMP-9 by regulating the NF-kB signaling in the bladder cancer cells." (PMID 24146910, 2013). "On the other hand, ROCK1-induced high level of c-Met, MMP2 and MMP9, which enhances migration and invasion of bladder cancer cells." (PMID 24180482, 2013). "In our study, MMP-9 was the most detectable gelatinases in the urine of bladder cancer patients which means a relative excess level of MMP-9 relative to TIMP-1 produced by the primary tumor and surrounding stroma." (PMID 23672427, 2013).
bladder cancer (continued). "In previous studies, p38 MAPK activation was demonstrated to regulate MMP2, MMP9 the activity of c-Met and can promote invasion of bladder cancer." (PMID 24180482, 2013). "Inoue K. and colleagues demonstrated that IL-8 enhanced angiogenic activity by induction of MMP9 expression and subsequently regulated the tumorigenicity and metastasis in human bladder cancer." (PMID 22811589, 2012). "The present results indicate that transcription factors NF-κB and AP-1 are the main factors for MMP-9 induction in response to IL-5, IL-20, and IL-28A in bladder cancer cells." (PMID 22962576, 2012). "The preclinical evidence supporting a role for MMP-9 in bladder cancer metastasis has been elucidated, in which increased MMP-9 expression correlates directly with high-grade and advanced-stage bladder tumors." (PMID 22962576, 2012). "p38 MAPK mediates TNFα-induced MMP-9 expression, thus leading to the progression of human urinary bladder cancer cells." (PMID 21859479, 2011). "•MMP-9 is a potential therapeutic target in bladder cancer progression." (PMID 41273852, 2025). "Similarly, downregulation of EMMPRIN (an extracellular MMP inducer, also known as CD147 represses MMP-9 expression, leading to decreased proliferation, migration, and invasion of bladder cancer cells." (PMID 41273852, 2025). "Notably, microRNA-145 is significantly downregulated in bladder cancer, leading to a marked reduction in the expression of N-cadherin and its downstream effector molecule matrix metalloproteinase-9 (MMP9)." (PMID 40689207, 2025). "MMP-9 is an important prognostic indicator for bladder cancer and can be a vital biomarker tool." (PMID 41002342, 2025). "•CRISPR/Cas9 effectively silenced MMP-9 in bladder cancer cells." (PMID 41273852, 2025). "Moreover, Royal jelly decreases the expression of the apoptotic gene (MMP-9) responsible for bladder cancer in humans." (PMID 38500210, 2024). "TMZ also upregulated MMP9 activity in 5637 bladder cancer cells." (PMID 38906916, 2024). "Indeed, a strong correlation between decreased E-cadherin levels and increased MMP9 expression was observed in bladder cancer." (PMID 39739829, 2024). "Moreover, IL-7 promotes cell migration and invasion by upregulating Erk1/2-mediated MMP-9 expression in bladder cancer cells." (PMID 36672342, 2023). "Finally, it has also been shown that -Cresol causes DNA damage in enterocytes in a dose-dependent manner and is able to promote the invasion and migration of tumor cells by increasing MMP9 expression in bladder cancer." (PMID 37372437, 2023). "However, in contrast to uc.416 + A expression in renal cell carcinoma, the expression of uc.8 + is negatively correlated with the grade of bladder cancer by increasing the expression of matrix metalloproteinase 9 (MMP9)." (PMID 37036543, 2023). "Moreover, it seems that MMP-9 has higher clinical utility than MMP-2 as a potential therapeutic option and a diagnostic biomarker of urinary bladder cancer." (PMID 36979935, 2023). "Therefore, the aim of the study was to evaluate the expression and activity of matrix metalloproteinase 2 and 9 (MMP-2 and MMP-9) in urinary bladder cancer according to different stages." (PMID 36979935, 2023). "In addition, recent investigations have highlighted the inhibitory effect of miR-300 exerted on bladder cancer cell metastasis by virtue of down-regulating MMP9." (PMID 35504875, 2022). "Collectively, our findings unraveled a LINC00478-mediated inhibitory mechanism in bladder cancer via the recruitment of histone demethylation transferase KDM1A to the MMP9 promoter region, which can provide potential implications for novel therapeutic targets against bladder cancer." (PMID 35504875, 2022).
bladder cancer (continued). "Furthermore, the results of Western blot illustrated that the expression of N-cadherin, Vimentin, and MMP9 was decreased in bladder cancer cells after over-expression of LINC00478 in T24 cells while being elevated following LINC00478 silencing in 5637 cells." (PMID 35504875, 2022). "EGFR activation has also been reported to induce MMP‐9 expression in bladder cancers." (PMID 36448260, 2022). "Moreover, silencing MMP9 leads to the suppression of migration in bladder cancer cells, indicating that interruption of the basement membrane by MMP9 plays an indispensable role in promoting bladder cancer cell motility and migration." (PMID 35504875, 2022). "In lieu of the preceding evidence, we speculated the involvement of LINC00478 in bladder cancer progression via the mediation of KDM1A-dependent MMP9 demethylation." (PMID 35504875, 2022). "Additionally, our data unveiled that silencing of MMP9 exerted a repressive effect on bladder cancer cell malignant phenotype in vitro, and also diminished tumor growth and lung metastasis in vivo." (PMID 35504875, 2022). "Furthermore, LINC00478 is capable of suppressing the progression of bladder cancer through down-regulation of MMP9 by interacting with KDM1A." (PMID 35504875, 2022). "In addition, MMP9 expression was enhanced in bladder cancer cells (T24, UM-UC3, HT-1197, and 5637) relative to that in normal bladder epithelial cells (SV-HUC-1), with T24 cells exhibiting the highest expression." (PMID 35504875, 2022). "Also in bladder cancer, elevated IL-5 levels enhance bladder cancer cell migration and invasion through the extracellular signal-regulated kinase 1/2-mediated matrix metallopeptidase 9/nuclear factor κ/activator 1 pathway." (PMID 36531035, 2022). "Furthermore, we investigated the effects of LINC00478 and MMP9 on the growth of bladder cancer in vivo." (PMID 35504875, 2022). "The high expression of MMP-9 can promote the metastasis of bladder cancer has been confirmed, and there is evidence that the process is associated with MMP-9 promoted epithelial-mesenchymal transition (EMT) in bladder cancer." (PMID 34869390, 2021). "Researchers have demonstrated that MMP9 is significantly associated with poor survival of cancer patients by way of promoting the invasiveness of cancer cells, and high expression of MMP9 has been observed in bladder cancer patients with poor prognosis and rapid tumor progression." (PMID 33465047, 2021). "Finally, significantly increased levels of MMP-2 and MMP-9 were detected in the urine of bladder cancer patients, meaning that both MMPs also serve as bladder tumor-specific markers." (PMID 34199232, 2021). "For instance, the invasion and metastasis of bladder cancer cells was reported to be substantially regulated by the hsa_circ_0001361, via directly sponging the miR-491-5p to promote the expression of matrix metalloproteinase 9 (MMP9) gene." (PMID 35071227, 2021). "The present results provide evidence that MSSV could impair MMP-9 expression by decreasing the binding activities of AP-1 and Sp-1 motifs, and thereby weakening the migration and invasion capabilities of bladder cancer cells." (PMID 33430488, 2021). "Furthermore, it has an effect on promoter-matrix metalloproteinase-9 (MMP-9), which is a key regulator and participates in the metastasis of bladder cancer cells." (PMID 34203479, 2021). "In addition, baicalin inhibits bladder cancer cell invasion by attenuating matrix metallopeptidases (MMPs) levels including MMP-9 and MMP-2 in bladder carcinoma 5637 cells." (PMID 33996570, 2021). "In summary, TAM-derived CXCL8 can promote the expression of MMP-9, VEGF, and E-cadherin in bladder cancer cells, causing changes in bladder cancer cell migration, invasion, and pro-angiogenic ability, and leading to the progression of bladder cancer." (PMID 32201645, 2020).